CSPG4 (chondroitin sulfate proteoglycan 4)
Diseases named in the same sentence as CSPG4 in open-access papers (continued):
Sharing a sentence is not in itself a finding about the gene and the disease.
melanoma (continued). "This theory is supported by findings of improved survival in melanoma patients who endogenously generated CSPG4-targeted antibodies." (PMID 36110930, 2022). "While CSPG4 has been widely studied in certain malignancies, such as melanoma, evidence is emerging from global gene expression studies, which suggests a role for CSPG4 in squamous cell carcinoma (SCC)." (PMID 36428658, 2022). "One other potential ADC target for melanoma that is gaining interest is chondroitin sulphate proteoglycan 4 (CSPG4)." (PMID 36140259, 2022). "It was reported that infusing chondroitin sulfate proteoglycan-4 (CSPG4)-specific CAR-T cells into NOD SCID gamma mice engrafted with the human melanoma WM115 cells showed superior antitumor activity following photothermal ablation of the tumor." (PMID 36159668, 2022). "Previous reports show that, in several melanoma cells, expression of differentiation antigens (Tyrosinase, Melan-A or CSPG4) increased after short-term treatment with BRAFi followed by a decrease at long-term, affecting T cell recognition." (PMID 36726591, 2022). "The chondroitin sulfate proteoglycan 4 (CSPG4) has been identified as a target for many cancers including melanoma, leukemia, glioblastoma, and TNBC." (PMID 35795050, 2022). "Significant difference in antibody response to epitopes of known melanoma antigens CSPG4 (#4), PMEL (#6) and TGO1 (#31) was noticeable between PEM-Mel and MelVac and their respective control groups (Wilcoxon Rank Sum test, p < 0.001)." (PMID 35603273, 2022). "We aimed to evaluate the potential of the well-established melanoma antigen chondroitin sulfate proteoglycan 4 (CSPG4) as an inducible antigen in ovarian cancer cells, using CSPG4-negative SKOV-3 ovarian cancer cells as a model." (PMID 36291817, 2022). "In hepatocellular carcinoma, Glypican-3-specific CAR-NK T-cells also mediated potent antitumor activity while the chondroitin sulfate proteoglycan 4 (CSPG4) CAR-NK T-cells demonstrated the efficacy against melanoma." (PMID 36569859, 2022). "CAR T cells labeled with carboxyfluorescein succinimidyl ester (CFSE) were co-cultured with CSPG4 expressing human melanoma cells (WM115) for 3 days." (PMID 35265340, 2022). "Making use of decitabine (5-aza-2′-deoxycytidine), which is a well-characterized demethylating substance, a dose-dependent upregulation of CSPG4 on several melanoma cell lines was observed." (PMID 36291817, 2022). "Several studies have identified CSPG4 as a possible marker of malignancy in a range of tumours, including pancreatic cancer, leukemia, melanoma, and glioma." (PMID 36428658, 2022). "Increased expression of CSPG4 (chondroitin sulfate proteoglycan 4) and of PD-L1 in human melanoma cells are also dependent on galectin-3." (PMID 36361933, 2022). "Previous investigations have identified CSPG4 as a key gene in soft-tissue sarcoma, melanoma, and glioblastoma." (PMID 35127724, 2021). "In this study, CAR T cells which target to the chondroitin sulfate proteoglycan-4 (CSPG4) antigen overexpressed in melanoma (e.g., WM115 cell line) were prepared." (PMID 34158866, 2021). "Another melanoma antigen called chondroitin sulphate proteoglycan-4 (CSPG-4) has been used to develop a canine vaccine." (PMID 35053051, 2021). "Another review on this topic also discussed the future promise of several molecular targets for CAR T cell therapy in melanoma, including CSPG4, GD2, CD70, CD20, gp100, and NY-ESO-1." (PMID 34207884, 2021). "We investigated the proteomic profiles of sEV immunoselected using anti‐CSPG4 antibodies from 15 melanoma patients’ plasma." (PMID 33613873, 2021). "Chondroitin sulfate proteoglycan 4 (CSPG4) is a tumor-associated surface antigen, firstly found on human melanoma cells." (PMID 34440182, 2021). "CSPG4-expressing A375 human melanoma xenografts implanted in NOD-scid IL2rg-/- mice were also engrafted with human immune cells by intravenous administration." (PMID 34513315, 2021).
melanoma (continued). "Another prominent melanoma-specific tumor antigen is the high molecular weight melanoma-associated antigen (HMW-MAA), also called chondroitin sulphate proteoglycan 4 (CSPG4), which is present in more than 90% of melanomas." (PMID 34572949, 2021). "Firstly, we demonstrated similar binding kinetics of the unconjugated anti-CSPG4 antibody compared with the anti-CSPG4-(PDD) ADC in three melanoma cell lines with high and low expression of CSPG4." (PMID 32331483, 2020). "In summary, we present the first example of an ADC targeting the neural crest antigen CSPG4, that has potent anti-melanoma activity." (PMID 32331483, 2020). "CSPG4-targeting antibodies have also been used to deliver immunotoxins to CSPG4-expressing melanoma cells, which were then released from endo-lysosomal compartments into the cytosol by photochemical internalization." (PMID 32331483, 2020). "Multiple retrospective studies using the MCAM/CSPG4 CellSearch® Kit have found that CTC levels detected at baseline correlates with overall survival in late-stage melanoma." (PMID 32984308, 2020). "A neural crest marker, CSPG4 participates in melanoma pathogenesis and progression through activation of key signaling pathways (e.g., MAPK/ERK1,2) and through the promotion of sustained high-level activating signals required for malignant progression." (PMID 32331483, 2020). "To evaluate targeting cancer cells with our ADC, we selected CSPG4 high-expressing melanoma cells (A375, A2058) and CSPG4 low-expressing melanoma (SBCL-2) and breast cancer (SKBR-3) cell lines." (PMID 32331483, 2020). "Next, to gain an insight into the potential mechanism by which anti-CSPG4-(PDD) exerted cytotoxicity towards melanoma cells, CSPG4-high A375 and CSPG4-low WM-1361 cells were quantified after four and seven days of treatment with PBS and anti-CSPG4-(PDD)." (PMID 32331483, 2020). "In concordance, we confirmed antibody internalization by A375 melanoma cells in a time-dependent manner by confocal microscopy analysis of fluorescently labelled anti-CSPG4 antibody." (PMID 32331483, 2020). "Radiation upregulated B7-H3 and CSPG4 expression on BRAF wild type human MV3 melanoma cells treated with a BRAF inhibitor." (PMID 32894202, 2020). "Chondroitin sulfate proteoglycan 4 (CSPG4) was used for separation of melanoma-derived TEX, referred to as MTEX, from vesicles released by non-malignant cells." (PMID 32709086, 2020). "In fact, one study found that of 31 melanoma patients with CTCs detectable by other markers, only 42% had CSPG4-positive CTCs, suggesting a need for multi-marker approaches." (PMID 32984308, 2020). "Overall, CSPG4 is a relevant surface marker for melanoma CTCs and is hence evaluated in many studies." (PMID 32984308, 2020). "In high CSPG4-expressing A375 and A2058 human melanoma cells, anti-CSPG4-(PDD) as well as PDD alone significantly reduced cell viability at low nanomolar levels after 4 days." (PMID 32331483, 2020). "Clinical-scale production of mRNA IVT CAR T cells redirected against melanoma-targeted CSPG4 was reported." (PMID 32899932, 2020). "Anti-CSPG4-(PDD) inhibited CSPG4-expressing melanoma cell growth and colony formation and triggered apoptosis in vitro at low nanomolar to picomolar concentrations without off-target Fab-mediated or Fc-mediated toxicity." (PMID 32331483, 2020). "Analysis of RNA suggested that CSPG4+ CTCs were distinct from CTCs enriched by another melanoma marker, ABCB5." (PMID 32984308, 2020). "Treatment with anti-CSPG4-SB-Saporin for 4 days decreased tumor cell viability in CSPG4-high A375 and A2058 melanoma cell lines, while it had low toxic effects on the CSPG4-low SBCL-2 melanoma and SKBR-3 breast cancer cells." (PMID 32331483, 2020). "Most recently, ABT-737 and two other BH3 mimetics were tested in combination with a chondroitin sulfate proteoglycan 4 (CSPG4)-targeting immunotoxin in patient-derived melanoma, glioblastoma, and breast cancer cell lines and demonstrated significant synergy." (PMID 32630017, 2020).
melanoma (continued). "Together the reporter and imaging findings suggest that anti-CSPG4-IgG1 internalization occurred in CSPG4- expressing melanoma cells." (PMID 32331483, 2020). "Together, these findings indicated that anti-CSPG4-(PDD) can exert Fab-mediated cytotoxicity towards melanoma cells in an antigen-specific manner, with lower Fc-mediated cytotoxicity to immune cells." (PMID 32331483, 2020). "Chondroitin Sulfate Proteoglycan 4 (CSPG4) is involved in tissue development and can be a transmembrane receptor allowing for melanoma motility." (PMID 33339193, 2020). "As target cells, either the human TxB cell hybridoma T2.A1 (HLA-A2+, CSPG4−, gp100−) or the human melanoma cell line A375M (HLA-A2+, CSPG4+, gp100−), both either unpulsed or pulsed with the HLA-A2-restricted peptide gp100280–288, were used." (PMID 31137488, 2019). "T cells, retrovirally transduced with a CSPG4-specific CAR, exerted potent cytotoxicity in various CSPG4-expressing tumors, such as melanoma, breast cancer, mesothelioma, glioblastoma, and osteosarcoma, in animal models." (PMID 31195686, 2019). "Our production process was robust and resulted in a sufficient number of CSPG4-CAR-transfected T cells with a high potency to kill melanoma target cells." (PMID 31426437, 2019). "Nevertheless, CSPG4 is a prime tumor target antigen, since it plays a role in the metastasizing of melanoma, and is expressed on activated pericytes during angiogenesis in tumors and hypoxia, the latter making targeting of tumor vasculature possible." (PMID 31426437, 2019). "Mechanistically, melanoma growth is supported by ERK signaling downstream of CSPG4 and subsequent activation of the MAPK-pathway, which directs proliferation and counteracts pro-apoptotic signals." (PMID 31779130, 2019). "In summary, these data show that our CSPG4-CAR-transfected T cells had a very high potency to lyse CSPG4-positive melanoma target cells, and produce cytokines antigen-specifically." (PMID 31426437, 2019). "In the following we will discuss the merits and challenges of CSPG4 as a target for the CAR-T-cell therapy of melanoma." (PMID 31779130, 2019). "We labeled the CSPG4-negative target cell line 293T with 0.25 μM CFSE and the CSPG4-positive melanoma cell line A375M with 2.5 μM CFSE." (PMID 31426437, 2019). "Similar to melanoma and contrary to leukemia, CSPG4 acts as an oncogenic driver delivering growth promotion and survival signals to GBM cells." (PMID 31779130, 2019). "CSPG4-specific monoclonal antibodies, radio-immunoconjugates, or immunotoxins were already applied in animal models and melanoma patients, with partially promising results." (PMID 31426437, 2019). "We have previously shown that T cells equipped with a CAR derived from the 9.2.27 anti-CSPG4 antibody antigen-specifically eliminated melanoma cells." (PMID 31195686, 2019). "Another challenge for CSPG4-CAR-T-cell therapy of melanoma, derives from the presence of soluble CSPG4 in the bloodstream, which is generated by cleavage of the ectodomain of CSPG4." (PMID 31779130, 2019). "The repercussions of CSPG4 blockade or down-regulation on melanoma progression can be deduced from experiments blocking the expression or activity of CSPG4." (PMID 31779130, 2019). "Human melanoma cells A375M, which evince a strong CSPG4 expression, served as positive control for CSPG4-CAR T cell activity throughout this study." (PMID 31195686, 2019). "The aim of the current study was to extrapolate our experience in targeting melanoma cells with CSPG4-CAR T cells to CSPG4-postiive MLL leukemias using MLL1-MLLT1-translocated KOPN8 B-ALL cells as target cells." (PMID 31195686, 2019). "For example, activation of the RAS/RAF pathway drives the expression of CSPG4, the most commonly used surface protein, to enrich melanoma CTCs." (PMID 31671846, 2019).
melanoma (continued). "CSPG4 is expressed on almost all melanoma cells, but also on uveal melanoma, and on other tumors like sarcomas, astrocytomas, gliomas, neuroblastomas, leukemias, and triple negative breast cancer." (PMID 31426437, 2019). "This study describes the establishment of the clinical-scale production of CAR-T cells for the treatment of melanoma patients by mRNA transfection of a CSPG4-specific CAR under full GMP in direct preparation of a clinical trial using these cells." (PMID 31426437, 2019). "Correspondingly, sh-RNA-mediated abrogation of CSPG4 expression in a subcutaneous model of A375M melanoma impaired melanoma proliferation and increased the percentage of apoptotic and necrotic tumor cells." (PMID 31779130, 2019). "Human melanoma cells (A375M) served as a positive control for the stimulation of CSPG4-CAR T cells and correspondingly induced upregulation of CD25 and CD69 expression on CSPG4-CAR T cells." (PMID 31195686, 2019). "The proteoglycan CSPG4 has been found on the surface of melanoma cells, MLL-rearranged leukemia cells, glioblastoma cells, and triple-negative breast cancer." (PMID 31779130, 2019). "In contrast, CSPG4-CAR-transfected T cells had a very high potency to lyse the melanoma cells at all target to effector ratios." (PMID 31426437, 2019). "These modifications permitted selection of melanoma cells specifically (e.g., CSPG4-positive, CD45-negative, FAP-negative population)." (PMID 31727958, 2019). "Activation of the RAS/RAF pathway has been suggested to increase the expression of the melanoma surface marker CSPG4 in neural cells." (PMID 31671846, 2019). "CSPG4 is expressed in the majority of melanoma cells, and owing to its distinct role in promoting metastasis formation and cell motility, it is usually preserved on the surface of melanoma metastases." (PMID 31779130, 2019). "Several lines of evidence, which have accumulated over recent years, suggest that CSPG4 fosters melanoma evolution by procuring growth signals and anti-apoptotic signals." (PMID 31779130, 2019). "The human lymphoma cell line T2.A1 (CSPG4−, CEA−) and the human melanoma cell line A375M (CSPG4+, CEA−) served as target cells." (PMID 30103488, 2018). "We prepared fluorescent beads coated with antigens extracted from human melanoma SK-MEL-28 cells, which natively express the tumor-associated antigen chondroitin sulfate proteoglycan 4 (CSPG4)." (PMID 29628923, 2018). "Four hours after electroporation these CAR-T cells were co-incubated with the CSPG-negative cell line T2 and the CSPG4+ melanoma cell line A375M at a 1:1 ratio in the absence or presence of the different kinase inhibitors." (PMID 29346301, 2018). "NG2/CSPG4 has been used as an immunotherapy target in xenografts in melanoma, triple-negative breast cancer, and malignant mesothelioma." (PMID 29196603, 2018). "An antigen-specific cytokine response was detected after co-cultivation of the cells transfected with the CSPG4-specific receptor with the melanoma cell line A375M, confirming the functionality of the CARs." (PMID 30103488, 2018). "In this study, we used Inovio’s proprietary SynCon® technology to design a synthetic consensus DNA vaccine targeting CSPG4 (SynCon® CSPG4) and assessed its immunogenicity and preclinical efficacy in a tumor-bearing mouse model of melanoma." (PMID 30400835, 2018). "We performed two veterinary trials to evaluate the potential of a xenogeneic DNA vaccine coding for the human CSPG4 in canine melanoma patients affected by spontaneous stage II-III CSPG4-positive oral melanomas." (PMID 29534457, 2018). "A transmembrane proteoglycan, CSPG4 plays a key role in stabilizing cell-substratum interactions in early melanoma cell invasion." (PMID 30333973, 2018). "In summary, the receptor-transfected NKT cells are capable of specifically lysing human melanoma cells after being equipped with CSPG4-specific CARs." (PMID 30103488, 2018).
melanoma (continued). "All together, these findings highlight the great value of CSPG4 as a translational immunotherapeutic target in veterinary clinical practice, not only for melanoma but also for other tumor types." (PMID 28668095, 2017). "This is evident from the observation that treatment with an anti-CSPG4 monoclonal antibody (mAb) results in reduced growth and motility of melanoma cells." (PMID 28657611, 2017). "Disease-specific apoptosis induction by scFv:sTRAIL fusion proteins has been demonstrated for various malignancies, including αMCSP:sTRAIL which targets melanoma featuring over-expression of CSPG4." (PMID 28657611, 2017). "Several mAb targeting CSPG4 have been described which inhibit growth and progression of CSPG4-positive tumors, including mAb 9.2.27 (against melanoma), mAb 225.28 (against breast cancer) and mAb TP41.2 (against mesothelioma)." (PMID 28657611, 2017). "For these reasons several immunotherapeutic approaches against CSPG4 for the treatment of melanoma and other CSPG4-expressing tumor histoypes have been tested both in pre-clinical and clinical settings." (PMID 28668095, 2017). "In support, levels of soluble CSPG4 have been reported in the sera of healthy individuals and patients with melanoma." (PMID 29375561, 2017). "CSPG4, also known as melanoma- associated chondroitin sulfate proteoglycan (MCSP), has been extensively described in the melanoma literature and its expression associated with disease progression." (PMID 27926479, 2017). "The best-established implication regards the link between CSPG4 and melanoma progression that was first appreciated as a result of its widespread expression in the majority (85% or greater) of human melanomas." (PMID 28668095, 2017). "A more recent immune monitoring study identified that both healthy individuals and melanoma patients have circulating CSPG4-reactive CD4+ T cells." (PMID 29375561, 2017). "As in melanoma, functions of CSPG4 in glioblastoma are believed to be related to malignant progression through facilitating tumor cell interactions with collagen and promoting angiogenesis." (PMID 29375561, 2017). "Another study investigating anti-CSPG4 CAR T cells announced promising efficacy outcomes against melanoma, breast cancer and head and neck cancer in vitro and in vivo using cell line xenografts in mice." (PMID 29375561, 2017). "Among the neuroectodermal tumors, malignant melanoma is the most thoroughly characterized in terms of CSPG4 expression and functions." (PMID 29375561, 2017). "The mechanism by which CSPG4 affects melanoma progression is only partly understood, in particular the involvement of other receptor tyrosine kinases and the tumor microenvironment." (PMID 25997619, 2015). "We have previously reported on a mimotope-based vaccine against CSPG4 in a human melanoma xenograft model that resulted in reduction of tumor growth." (PMID 25997619, 2015). "In this study we showed that targeting CSPG4 in melanoma cells enhanced antiproliferative effects of vemurafenib in normoxic conditions and reduced the migratory capacity in hypoxic conditions." (PMID 25997619, 2015). "Polyclonal anti-CSPG4-antibodies reduced the Transwell migration of vemurafenib-treated, BRAF V600E-mutant and CSPG4-expressing melanoma cells in hypoxia." (PMID 25997619, 2015). "Six of the 8 melanoma lines were strongly positive for CSPG4 expression with an additional line, mel624.38, demonstrating intermediate expression." (PMID 25197555, 2014). "TP41.2-based CSPG4 CAR transduced T cells were cocultured with either melanoma line mel1300 or glioblastoma cell line LN443." (PMID 25197555, 2014). "CSPG4 has also been found in certain tumor cells, and has been shown to promote their malignant behavior and to impact the progression of melanoma, glioblastoma, chondrosarcoma and leukemia." (PMID 24932730, 2014).